TERT (telomerase reverse transcriptase)
Diseases named in the same sentence as TERT in open-access papers (continued):
Sharing a sentence is not in itself a finding about the gene and the disease.
cancer (continued). "It was also shown that TERT interacts with NFκB and co-activates the expression of several genes that are critical for cancer progression." (PMID 34048184, 2021). "The mechanisms of activation or silencing of TERT remain open to debate across somatic, cancer, and stem cells." (PMID 33802026, 2021). "Variations in telomerase activity across cancer types can be partially explained by TERT expression (Rho = 0.54, P = 0.003)." (PMID 33420056, 2021). "Correlation of copy number gain with TERT gene expression or telomerase activity in a variety of cancer types have been extensively reviewed." (PMID 33599797, 2021). "Collectively, TAF-I is involved in the maintenance of telomere DNA through the regulation of TERT transcription, then consequently the occurrence and/or recurrence of cancer cells." (PMID 34489496, 2021). "Beta-catenin and c-MYC promote the expression of TERT, which in turn interacts back with these oncogenic drivers, to regulate the expression of cancer-specific genes in what appears to be a feed-forward loop." (PMID 33599797, 2021). "TERT is significant in carcinogenesis and, because of that, is a potential target for cancer treatment." (PMID 33802026, 2021). "We found that TERT mRNA and telomerase activity varied during the cell cycle and were able to affect the accuracy of cancer identification." (PMID 34691667, 2021). "Apart from the two hotspot mutations (C228T and C250T), the TERT promoter SNP rs2853669 is also common in several cancers and is predicted to decrease TERT expression." (PMID 34439356, 2021). "This issue is exacerbated by the low expression of TERT, which was estimated to be between 1 and 40 copies per cell in cancer cells." (PMID 33420056, 2021). "The activating TERT promoter mutations and BRAFV600E mutation are well-established oncogenic alterations in human cancers." (PMID 33483600, 2021). "On the basis of this system, we tested TERT mRNA and telomerase activity between different phases of cancer cells vs. normal cells." (PMID 34691667, 2021). "We subsequently analyzed the expression and promoter methylation level of TERT between cancer samples and matched normal bladder samples in the TCGA-BLCA cohort." (PMID 34055593, 2021). "TERT, on the other hand, is reactivated in most malignancies, and by lengthening telomeres, it contributes to cancer development and progression." (PMID 34853590, 2021). "TERT is reactivated by somatic TERT alterations or epigenetic modulations that result in development and progression of cancers by lengthening of telomeres." (PMID 34831001, 2021). "This cancer gene has been previously identified as a main target for HBV insertions, which are the cause of TERT focal amplification and TERT promoter activation." (PMID 34824211, 2021). "TERT promoter mutations were observed at the same hotspot (−124, −141 bp from TSS) similar to the other adult cancers that included HCC." (PMID 34538872, 2021). "It is suggested that rs401681 confers cancer susceptibility by regulating CLPTM1L and TERT expression, both genes implicated in carcinogenesis." (PMID 33879152, 2021). "One of the pathways being influenced RMRP is stem cells metabolism which accords with the formerly reported role of RMRP in giving permission to cancer cells for infinite proliferation via interplay with TERT." (PMID 33996836, 2021). "In most human primary cancers, the expression, or telomerase activity, of telomerase reverse transcriptase (TERT) is detectable." (PMID 34482792, 2021).
cancer (continued). "Taken together, these results suggest that TAF-I is generally involved in TERT transcription through the alterations of CpG methylation around TERT TSS in several kinds of cancer cells." (PMID 34489496, 2021). "For example, the mutation hotspot in the TERT promoter creates a TFBS of the ETS TF family that leads to constitutive activation of TERT and enables replicative immortality of cancer cells." (PMID 33941236, 2021). "Analysis of tissue and cancer-subtype specific TERT expression patterns uncovered heterogenous expression, regulation, and the potential impact of variable telomere maintenance on tumorigenesis." (PMID 33924498, 2021). "TERT mRNA expression and telomerase activity were significantly increased in over 80% of human cancers from tissue specimens." (PMID 34691667, 2021). "A positive feedback loop between DNMT3B and TERT has been suggested through a positive correlation in their expression in a wide range of cancer types within the Cancer Genome Atlas (TCGA) dataset." (PMID 33802026, 2021). "Alternatively, TERT amplification, as well as overexpression or amplification of cancer-driving oncogenes like MYC, which binds TERTp, can lead to elevated TERT expression." (PMID 34532611, 2021). "A possible application in cancer therapy is using CRISPR dCas9 to demethylate the TERT promoter region to reduce telomerase activity." (PMID 33802026, 2021). "Leveraging GWAS summary statistics for fourteen cancers, we observed pairwise local genetic correlations in the 5p15.33 region, harboring the TERT and CLPTM1L genes." (PMID 34355204, 2021). "Herein, we investigated the role of cell cycle progression (G0/G1, G1/S, S and G2/M phase) in analyzing telomerase (TERT mRNA and telomerase activity) in cancer cells based on an AIEgen-based fluorescence detecting system." (PMID 34691667, 2021). "Translocation of TERT into mitochondria improves mitochondrial potential which eventually leading to cancer cell survival." (PMID 33329574, 2020). "Telomerase reverse transcriptase (TERT)—the catalytic subunit of telomerase—is reactivated in up to 90% of all human cancers." (PMID 32599885, 2020). "In a screening of various oncoviruses like HPV, BKV, and EBV in various types of cancers, Chen and colleagues have confirmed the insertion at TERT locus, but the integration of breakpoints was in regions other than TERT locus." (PMID 32674474, 2020). "Particularly in neuroblastoma (cancer of immature nerve cells called neuroblasts commonly occurring in infants and young children), TERT locus rearrangements have been reported to be frequent and segregate with aggressive tumors." (PMID 32674474, 2020). "This points at RT domain as the necessary and sufficient as well as safe component of therapeutic cancer vaccines based on TERT." (PMID 32570805, 2020). "High telomerase activity is considered one of the six hallmarks of cancer proposed by Hanahan and Weinberg in 2000; therefore, targeting TERT/telomerase has long been considered to be a promising target for cancer drug development." (PMID 31963842, 2020). "The telomerase reverse transcriptase (TERT) gene is responsible for telomere maintenance in germline and stem cells, and is re-expressed in 90% of human cancers." (PMID 32267900, 2020). "In most cancers, TERT expression is reactivated and overexpressed during tumorigenesis leading to replicative immortality." (PMID 32850388, 2020). "DFT1 chromosomes have short telomeres compared with those of normal devil cells, but the cancer is known to express telomerase reverse transcriptase TERT." (PMID 33232318, 2020). "In summary, current data support the assumption that TERT promoter activity can be regulated by epigenetic mechanisms in a tissue- and cancer-type-specific manner." (PMID 32722302, 2020). "Studies of TERT alternative splicing in multiple cancer types have shown the highest expressed isoform in cancer is the full-length isoform, which correlates with higher telomerase activity." (PMID 32849278, 2020).
cancer (continued). "Based on a handful of identified and validated peptides, it appears clear that cancer patients often display CD4 T cell reactivity against TERT." (PMID 32630460, 2020). "Telomerase activity via TERT expression has an impact on telomere length and can be a useful marker in diagnosis and prognosis of various cancers and a new therapy approach." (PMID 33329574, 2020). "Telomerase regulation, including TERT promoter methylation, has been of long‐standing interest to cancer biologists." (PMID 32920953, 2020). "Telomerase reverse transcriptase (TERT) is pathologically expressed in the vast majority of human cancers, but the epigenetic regulation of its expression is only beginning to be understood." (PMID 33245585, 2020). "Overall, it appears that hypomethylation of the TERT proximal promoter is important for TERT expression in cancer cells." (PMID 33245585, 2020). "Benign and malignant tumours were positive for TERT mRNA expression, however the frequencies in which the expression was detected in each group were significantly different (p < 0.0001)." (PMID 32659948, 2020). "The trend of relative expression (cancer vs. healthy tissues) was indeed more favourable for Survivin/BIRC5 than for TERT." (PMID 32152425, 2020). "Mizukoshi and Kaneko have reviewed several TERT-derived immunogenic peptides as targets for cancer immunotherapy." (PMID 32674474, 2020). "TERT mRNA expression is present both in benign and malignant tumours, with a higher frequency in the malignant tumours, even in the absence of TERTp mutations." (PMID 32659948, 2020). "Several studies showed that there were some specific factors which regulated the expression of TERT in cancers." (PMID 33061812, 2020). "Taken together, these findings indicate that targeting TERT intracellular trafficking is a viable anti-cancer approach." (PMID 32599885, 2020). "Some cancer-related SNPs at five loci—TERT, butyrophilin-like 2, TP63, bromodomain PHD finger transcription factor, and high-mobility group box protein 1—showed significant effects on EGFR-mutated LADC." (PMID 33126605, 2020). "documented that hypermethylation of the TERT gene correlates with telomerase activity in different types of cancers." (PMID 33329574, 2020). "Most cancers, in contrast to most normal cells, show TERT expression upregulation changing transcriptional regulation, alternate RNA splicing, and post-translational modifications such as protein phosphorylation." (PMID 32932803, 2020). "We found that GABPA is a key factor in determining TERT transcription status in mammals of different evolutionary groups, similarly to certain human cancer cells." (PMID 33257697, 2020). "STAT3 has been reported to directly regulate TERT expression in several types of human cancer cells by binding to the promoter region of TERT30." (PMID 32257389, 2020). "The therapeutic efficacy of the first identified MHC-II TERT peptides has been evaluated in cancer patients." (PMID 32630460, 2020). "A proportion of hOSCC is associated with infection by high-risk human papillomavirus (HR-HPVs), whose E6 oncogene enhances TERT and MMPs expression, thus promoting cancer progression." (PMID 32292795, 2020). "This would explain the observation that TERT expression is relatively low in the majority of cancers, just sufficient to maintain telomere lengths that are already relatively short compared to normal cells." (PMID 32468444, 2020). "Of relevance, the RBPs hnRNPF/H have been reported to regulate the activity of TERT upon binding to both enzyme and RNA components, contributing to cancer and human mesenchymal stem cell proliferation and senescence." (PMID 33391635, 2020).
cancer (continued). "We propose that monitoring CD4 T cell immunity against TERT is a simple and direct way to assess immune surveillance in cancer patients and a new way to predict the response to immune checkpoint inhibitors (ICPi)." (PMID 32630460, 2020). "In this review we want to highlight the main roles of TERT in different mechanisms of cancer development and regulation." (PMID 33329574, 2020). "TERT plays a key role in cancer formation, ensuring chromosomal stability by maintaining telomere length, and allowing cells to avert senescence." (PMID 33329574, 2020). "Accordingly, ectopic TERT expression enhances cancer cell migration and metastasis both in vitro and in vivo." (PMID 32599885, 2020). "TERT is silent in most somatic cells, and is reactivated in cancer cells, endowing them with unrestricted proliferation capacity." (PMID 32204305, 2020). "The thyroid tissue adjacent to benign and malignant tumours was TERT mRNA positive in 29% and 39% of the cases, respectively." (PMID 32659948, 2020). "GV1001 vaccination was evaluated in different cancer types either alone or in combination with MHC-I (HLA-A2.1) TERT peptides (p540) in granulocyte macrophage-colony stimulating factor (GM-CSF) adjuvant, with or without chemotherapy." (PMID 32630460, 2020). "TERT was reported to be significantly activated in various cancers, while its role in RCC remained to be elucidated." (PMID 33061812, 2020). "Such dysfunctional telomeres or telomer-like structures can be synthesized by rtTERT complemented with TERT RNA-binding domain (TRBD) of endogenous TERT in complex with the endogenous telomerase RNA template (TERC) abundant in cancer cells." (PMID 32570805, 2020). "Therefore, we speculated that TERT mutation might play a role in the majority of cancers." (PMID 32810393, 2020). "TERT expression was analyzed in 107 cancer cell lines that were previously classified as follows: WT promoter, MAE (n = 16); −124 and −146 promoter mutations, which cause MAE (n = 48); and WT, BAE (n = 43)." (PMID 33245585, 2020). "In particular, the active TERT gene in cancer cells has been characterized as having a hypermethylated CpG island, opposite to the general association of DNA methylation with gene repression." (PMID 33245585, 2020). "The presence of TERTp mutations was an uncommon finding in our series, whereas the expression of TERT mRNA was a common event in the malignant tumours (48% of the cases) and present in the benign tumours (17%)." (PMID 32659948, 2020). "We found this region to have significantly decreased methylation in TERT BAE cancer cells compared to MAE cells." (PMID 33245585, 2020). "For this, we assembled an epitopic map of TERT and localized regions containing clusters of T cell epitopes recognized by cancer patients and by animals (mainly mice) in the preclinical vaccine trials." (PMID 32570805, 2020). "Here, we investigated DNA methylation patterns in the TERT promoter across 23 different cancer tissue types and 833 different cancer cell lines." (PMID 33245585, 2020). "Regardless of its mechanism of action, which requires further studies to fully elucidate, TERT holds as a promising anti-cancer target gene." (PMID 31963842, 2020). "Telomerase negative primary cells exhibit high levels of the silencing H3K27me3 mark at the TERT promoter, compared to telomerase positive cancer cell lines, which exhibit the activating H3K4me3 mark." (PMID 32849278, 2020). "The reactivation of telomerase reverse transcriptase (TERT) protein is the principal mechanism of telomere maintenance in cancer cells." (PMID 32204305, 2020).
cancer (continued). "Taking in to account its major importance in cancer, TERT has become a target of various therapeutic strategies in cancer treatment and continues to be an interesting object of research." (PMID 33329574, 2020). "TERT gene codes for a telomere reverse transcriptase catalytic subunit, the principal mechanism of telomere maintenance in cancer cells." (PMID 32850962, 2020). "This comprehensive analysis makes a strong case for reconciling the previously diverging interpretations of the role of TERT promoter methylation patterns in cancer." (PMID 32920953, 2020). "The third reported mechanism is the insertional mutagenesis, which can integrate the viral DNA into host cancer genes (telomerase reverse transcriptase (TERT), myeloid/lymphoid or mixed-lineage leukemia 4 (MLL4), and cyclin E1 (CCNE1))." (PMID 31947702, 2020). "Further investigation is required in this field to understand the molecular and cellular events involved in alternative splicing regulation of TERT in normal development in various tissues and during cancer initiation and progression." (PMID 32674474, 2020). "Treatment with BIBR1532 decreases the protein expression of several MMPs in different types of cancer cells, through down-regulation of TERT." (PMID 33553285, 2020). "We have provided herein a comprehensive view of the role of CD4 T cell immunity against TERT in cancer." (PMID 32630460, 2020). "Identification of TERT promoter hotspot mutations (chr5, 1,295,228 C>T and 1,295,250 C>T; hereafter termed C228T and C250T, respectively) in cancers was one of the most pivotal events in understanding the mechanisms of TERT upregulation." (PMID 33061812, 2020). "In cancer, active expression of the TERT gene paradoxically correlates with a hypermethylated CpG island." (PMID 33245585, 2020). "Approximately 90% of all human cancers share a transcriptional alteration: reactivation of the telomerase reverse transcriptase (TERT) gene." (PMID 32267900, 2020). "With the advent of genome sequencing, the rearrangement of TERT locus has also been identified to occur in various cancers types." (PMID 32674474, 2020). "TERT reactivation can also be entirely epigenetic, and this appears to be the case for the majority of cancers." (PMID 33245585, 2020). "Cancer cells are positively selected to escape the native repressive chromatin environment in order to allow TERT transcription." (PMID 32267900, 2020). "The expansion of TERT-specific CD4 T cells in the peripheral blood of cancer patients correlates with a more favorable outcome of disease." (PMID 32630460, 2020). "As expected, TERC is constitutively expressed in all cells examined; whereas TERT is expressed in cancer cells (Hela, PANC1 and SUM15) and human induced pluripotent stem cells (iPSCs), but not in primary cells such as human aortic smooth muscle cells (HASMCs)." (PMID 31963842, 2020). "It seems that only TERT down regulation starts the entire pathway of inducing apoptosis and cancer cell elimination." (PMID 32856851, 2020). "The catalytic subunit, telomerase reverse transcriptase (TERT), is transcriptionally active in germline, stem, and cancer cells, but silenced in somatic cells, making it a gatekeeper of cellular immortalization while maintaining chromosomal integrity." (PMID 32920953, 2020). "The studies on mutations in the TERT and SDHD promoters highlight promoter-region mutations as important events that regulate the transcription of cancer regulatory genes by creating or abolishing transcription factor-binding sites." (PMID 33024276, 2020). "Frequent amplifications of the TERT gene have been shown in human cancer cell lines and in human tumors." (PMID 32722302, 2020). "In most human cancers, telomerase is reactivated during carcinogenesis by expression of the catalytic subunit telomerase reverse transcriptase (TERT)." (PMID 33329574, 2020).